CD244 (CD244 molecule)
Diseases named in the same sentence as CD244 in open-access papers (continued):
Sharing a sentence is not in itself a finding about the gene and the disease.
uveal melanoma (2 papers, 2024 to 2025). A melanoma derived from melanocytes of the uveal tract. "Additionally, concerning immunosuppressive gens, PLAG1 was significantly positively correlated with TIGIT, CD96, and CD244 in LGG, uveal melanoma, and liver hepatocellular carcinoma, indicating that it may facilitate the formation of a tumor immune-suppressive microenvironment." (PMID 40276502, 2025).
acute leukemia (1 paper, 2023). A clonal (malignant) hematopoietic disorder with an acute onset, affecting the bone marrow and the peripheral blood. "Further studies are required to perform functional assays on CD8+ T cells to elucidate the exact role of CD244 in acute leukemia." (PMID 37634081, 2023). "In this study, we focused on acute leukemia, including ALL and AML, and examined the relative mRNA expression of CD244 and its downstream adapter molecules, SAP and EAT-2, in CD8+ T cells." (PMID 37634081, 2023). "Study of CD244 and its adapter molecules, SAP and EAT-2, in CD8+ T cells in acute leukemia would be helpful to further understand T cell exhaustion-related pathways and to find therapeutic targets for acute leukemia." (PMID 37634081, 2023). "This study investigated the role of the ICR, CD244, and its adapter molecules, in CD8+ T cells in acute leukemia." (PMID 37634081, 2023). "Hence, this study aimed to investigate the expression of CD244 and its related adapter molecules in CD8+ T cells in acute leukemia." (PMID 37634081, 2023).
AIDS (1 paper, 2014). A syndrome resulting from the acquired deficiency of cellular immunity caused by the human immunodeficiency virus (HIV). "Expression of 2B4/CD244/p38 was lower in AIDS-RL than in HIV-negative lymphoma patients." (PMID 25908934, 2014). "Expression of 2B4/CD244/p38 was lower in AIDS-RL than in HIV-negative lymphoma." (PMID 25908934, 2014). "The AIDS-RL patients had decreased levels of 2 out of 3 NCRs, of NKG2D and of 2B4/CD244/p38." (PMID 25908934, 2014).
allergic disease (1 paper, 2021). An immune response that occurs following re-exposure to an innocuous antigen, and that requires the presence of existing antibodies against that antigen. "This leads to the conclusion that CD244 is critical for the initiation and continuation of allergic status, and that blockade of either CD244 or CD48 is a promising therapeutic strategy for treatment of allergic diseases." (PMID 33841431, 2021). "However, more studies of allergic diseases concentrated on CD48 rather than CD244." (PMID 33841431, 2021).
B-cell acute lymphoblastic leukemia (1 paper, 2025). A neoplasm of lymphoblasts committed to the B-cell lineage, typically composed of small to medium-sized blast cells. "Our study highlights the complex immune regulatory network involved in B-cell acute lymphoblastic leukemia (B-ALL), focusing on the interplay between VISTA, CD244, CD48, FOXD3, and PVRL2." (PMID 40610562, 2025).
B-cell lymphomas (1 paper, 2014). "The down-regulation of 2B4/CD244/p38 could thus impair the cytotoxicity against EBV-positive B-cell lymphomas." (PMID 25908934, 2014).
bone metastasis (1 paper, 2025). Transfer of a neoplasm from its primary site to bones. "Six proteins (CSF-1, CCL4, CCL3, CD83, IL-12, and CD244) and three clinical characteristics (LDH levels, bone metastasis status, and liver metastasis status) were incorporated into the predictive model." (PMID 40404633, 2025).
bovine tuberculosis (1 paper, 2020). "Inhibition of CD244 expression may promote the expression of IFN-γ/TNF-α in CD8+ T cells and may reduce the incidence and mortality of bovine tuberculosis." (PMID 32153632, 2020).
Breast Invasive Carcinoma (1 paper, 2021). "Of importance, lower expression levels of the PDE9A, Iqca1, Sirpb1b, CD244, SP140, and PIP5k1b genes was found in the BC patients with unfavorable prognosis in terms of 5-year survival analysis (dataset of Breast Invasive Carcinoma [n = 1075] from TCGA)." (PMID 33426510, 2021).
brucellosis (1 paper, 2024). Brucellosis is a bacterial infection that spreads from animals to people via unpasteurized dairy products or by exposure to contaminated animal products or infected animals. "The exhausted NK cells (NK_CD56(dim)) highly expressed multiple inhibitory molecules (e.g., LAG3, CD244, CTLA4) in brucellosis patients compared to healthy donors." (PMID 39135683, 2024).
Burkitt lymphoma (1 paper, 2024). A rare form of malignant mature B-cell non-Hodgkin lymphoma. "All analyzed Burkitt lymphoma cell lines (Raji, Daudi, Ramos, and Namalwa) were SLAMF4/CD244-negative." (PMID 38612827, 2024). "Another flow cytometry study confirmed the absence of SLAMF4/CD244 in Daudi, Namalwa, Raji, and Ramos Burkitt lymphoma B cell lines." (PMID 38612827, 2024).
chronic obstructive pulmonary disease (1 paper, 2024). A chronic and progressive lung disorder characterized by the loss of elasticity of the bronchial tree and the air sacs, destruction of the air sacs wall, thickening of the bronchial wall, and mucous accumulation in the bronchial tree. "This study delved into the interplay between CD244 and Src Homology 2 Domain Containing Phosphatase-2 (SHP2) in chronic obstructive pulmonary disease (COPD) pathogenesis, focusing on apoptosis and inflammation in cigarette smoke extract (CSE)-treated human bronchial epithelial (HBE) cells." (PMID 39423200, 2024).
colon cancer (1 paper, 2022). "CD244 can be classified as an immunosuppressive receptor—as shown in a recent study on a murine model of colon cancer—and, as such, can contribute to the immunosuppressive TME." (PMID 35682983, 2022).
dengue (1 paper, 2015). "A recent study showed that analysis of seven genes (LOC286087, SLC4A4, PSPH, MYOM2, CACNA2D3, CD244 molecule, SMAD5) could possibly predict severe dengue since their expression profile was significantly lower in DHF patients compared to patients with DF." (PMID 26462910, 2015).
Down syndrome (1 paper, 2022). "For CD4+ T cells, the percentages of PD-1+ and CD244+ expression were elevated in children with Down syndrome (mean 25.9 ± 2.0 and 7.6 ± 1.0, respectively), compared to controls (mean 12.9 ± 1.9 and 4.6 ± 0.9)." (PMID 35222360, 2022). "The levels of expression of the single receptor CD160+ and co-expression of all three inhibitory receptors, CD4+PD-1+CD160+CD244+ T cells, were similar for children with Down syndrome and healthy controls." (PMID 35222360, 2022).
Hypercholesterolemia (1 paper, 2013). An increased concentration of cholesterol in the blood. "The network in the MCA with largest number of up-regulated focus genes affected by hypertension plus hypercholesterolemia showed many molecules related to ERK 1/2, interferon alpha, IL12, SYK, CD2, CD4, and CD244." (PMID 23874591, 2013).
lymph node metastasis (1 paper, 2025). "The expression of SELENOP was not statistically significant concerning patient age (p > 0.05); however, differences in histological grade, lymph node metastasis, LAG-3, CD244, estrogen receptors, progesterone receptors, and Her-2 expression were statistically significant (p < 0.05)." (PMID 40821907, 2025). "The expression of PKMYT1 was not statistically significant concerning patient age, and lymph node metastasis (p > 0.05); however, differences in histological grade, LAG-3, CD244, estrogen receptors, progesterone receptors, and Her-2 expression were statistically significant (p < 0.05)." (PMID 40821907, 2025).
metastatic tumors (1 paper, 2024). "Furthermore, the presence of CD244-negative monocytes/macrophages significantly increased patient survival in primary and metastatic tumors." (PMID 38424542, 2024).
prostatitis (1 paper, 2025). An infectious or non-infectious inflammatory process affecting the prostate gland. "MR analysis indicates that CD244 is a risk factor for prostatitis." (PMID 40355178, 2025). "Interleukin-10 receptor A (IL-10RA), Natural Killer Cell Receptor 2B4 (CD244), and urokinase-type plasminogen activator (uPA) may contribute to the occurrence of prostatitis, while Interleukin-12B (IL-12B) appears to serve as a protective factor against it." (PMID 40355178, 2025). "The IVW analysis results for IL-10RA (IVWIL-10RA: OR = 1.242, 95% CI: 1.043–1.478, P = .015), CD244 (IVWCD244: OR = 1.143, 95% CI: 1.002–1.305, P = .047), and uPA (IVWuPA: OR = 1.141, 95% CI: 1.009–1.290, P = .035) indicated positive associations with the risk of prostatitis." (PMID 40355178, 2025).
uterine corpus endometrial carcinoma (1 paper, 2024). A endometrial carcinoma (disease) that involves the body of uterus. "In addition, we performed immunohistochemistry (IHC) to confirm the CD244 expression in uterine corpus endometrial carcinoma (UCEC)." (PMID 38633624, 2024).
vitiligo (1 paper, 2024). Generalized well circumscribed patches of leukoderma that are generally distributed over symmetric body locations and is due to autoimmune destruction of melanocytes. "Notably, proteins such as IL-17C, CXCL10, NKR2B4 (CD244), and TNF receptor superfamily member 11b (TNFRSF11B) exhibited bidirectional causality with vitiligo." (PMID 38660673, 2024).
tumor (103 papers, 2012 to 2025). "Current studies indicate that CD244 primarily transmits inhibitory signals in tumor-associated immune cells, resulting in immune cell dysfunction." (PMID 40072746, 2025). "In particular, mo-Mac clusters displayed high expression of Cd244, an inhibitory receptor proposed to suppress immune responses in tumor-associated myeloid cells." (PMID 41331250, 2025). "Mechanistically, we present for the first time that enhanced autophagy in CD244-deficient monocyte-lineage cells promotes the differentiation of anti-tumorigenic Ly6Clow macrophages within the tumor microenvironment." (PMID 38424542, 2024). "Taken together, these findings suggest that the specific loss of CD244 signaling in tumor-infiltrating monocytes favors the differentiation of Ly6Clow macrophages." (PMID 38424542, 2024). "We found that CD244 expression was down-regulated in many cancers as well as significant associations between CD244 expression and clinical pathological stages, tumor prognosis, and tumor functional states in various human tumors." (PMID 38633624, 2024). "To assess the direct impact of CD244 deficiency in CD244fl/flLysMcre mice, we first analyzed the myeloid cell populations within the tumor mass and compared it to those in control CD244fl/fl mice." (PMID 38424542, 2024). "We further investigated the association between CD244 expression and tumor-infiltrating immune cells, and discovered their positive correlation in different tumors." (PMID 38633624, 2024). "Meanwhile, data from the TISIDB database confirmed the positive association between the infiltration of CD8+ T cells and CD244 expression across multiple tumor types." (PMID 38633624, 2024). "In the myeloid compartment of the tumor microenvironment, CD244 signaling has been implicated in immunosuppressive phenotype of monocytes." (PMID 38424542, 2024). "We also studied the genetic mutations of CD244, CD244 promoter methylation level, tumor functional status related to CD244, and CD244 related co-expression molecules and related signaling pathways." (PMID 38633624, 2024). "The mutation status, promoter methylation, CD244-related molecules and signaling pathways were also employed to study the potential function of CD244 in tumor initiation and progression." (PMID 38633624, 2024). "Activation of CD244 in a lab setting was found to suppress the release of crucial pro-inflammatory cytokines in human DCs, and intriguingly, CD244-deficient mice demonstrated delayed HNSCC tumor progression." (PMID 37835502, 2023). "In a previous study, the receptor encoded by the CD244 gene was thought to modulate NK-cell cytolytic activity and predominantly displayed inhibitory signaling in tumor-associated immune cells." (PMID 34702300, 2021). "CD244 appears to predominantly propagate inhibitory signaling in tumor-associated immune cells, but the interplay of factors determining activating versus inhibitory signaling has not been fully elucidated." (PMID 30546369, 2018). "To investigate the underlying cause of the significant increase in CD244 expression on monocytes/macrophages following tumor induction, we conducted a comprehensive analysis utilizing public mouse single-cell RNA sequencing (scRNA-seq) data and performed ex vivo experiments." (PMID 38424542, 2024). "In addition, more studies are needed to delineate the specific functions of CD244 signaling in tumor-associated immunosuppression." (PMID 30546369, 2018). "Similarly, by using NK cell libDIA, an extra 165 proteins were identified, expanding the coverage to 7143 proteins and facilitating the exclusive identification of CD244, an immunoregulatory receptor that displays inhibitory signals in tumor-associated immune cells." (PMID 38810695, 2024). "The results showed that after stimulation with BLMP1/2A cells or T-ALL tumor cells, the expression of Klrk1 and Cd244 was significantly higher in CD8+ T cells from GCB-LMP1/2A mice compared to the control group." (PMID 40534857, 2025).
tumor (continued). "Our data reveal that CD244 suppresses anti-tumor immunity by decreasing monocytes differentiation through autophagy regulation as well as phagocytic and antigen-presenting functions of macrophages, leading to an attenuated adaptive immune response." (PMID 38424542, 2024). "Blocking CD244 on NK cells markedly attenuates the NK cell dysfunction induced by tumor-derived monocytes." (PMID 38633624, 2024). "In this study, we explored the CD244 expression profile across 33 tumor types based on The Cancer Genome Atlas project, the Gene Expression Omnibus database, and other bioinformatics tools." (PMID 38633624, 2024). "CD244 activation significantly impaired the production of proinflammatory cytokines, subsequently inhibiting tumor growth." (PMID 38633624, 2024). "Our study aimed at determining the effect of CD244 in the tumorigenesis and progression across various tumor types." (PMID 38633624, 2024). "This further illustrates that CD244 is a protective factor in oncogenesis and represents a potential biomarker for tumor prognosis." (PMID 38633624, 2024). "CD3EAP, SMAD9, and CD244 are considered valuable tumor markers, with CD3EAP particularly noteworthy as a tumor marker in smokers." (PMID 39092217, 2024). "In this study, we provide direct evidence using CD244fl/flLysMcre conditional knockout and CD244 whole knockout mice, that CD244 serves as a pivotal immune checkpoint receptor, impeding anti-tumor immunity within myeloid cells." (PMID 38424542, 2024). "As shown in the right, the percentage of CD244-expressing cells increased up to 71.0% in the monocytes and 61.2% in the macrophage population within tumor." (PMID 38424542, 2024). "Our results showed that representative CD244-expressing cells, such as NK cells and DCs, had constitutive expression of CD244 in both skin and tumor tissues." (PMID 38424542, 2024). "In this section, we explored the expression status of CD244 in normal and tumor samples with various pathological stages." (PMID 38633624, 2024). "While the adoptive transfer of CD244−/− BMDM into B16F10 tumor-bearing mice had a modest effect in suppressing tumor growth, the combination of CD244−/− BMDM and anti-PD-L1 antibody resulted in significant reduction in the growth of B16F10 tumors." (PMID 38424542, 2024). "Further research and validation are needed in each tumor to study the relationship between CD244 and the biological processes of EMT, differentiation, invasion, hypoxia, and DNA repair." (PMID 38633624, 2024). "Combining anti-PD-L1 antibody with CD244−/− bone marrow-derived macrophages markedly improved tumor rejection compared to the anti-PD-L1 antibody alone or in combination with wild-type macrophages." (PMID 38424542, 2024). "Collectively, these data demonstrate that CD244 on monocyte-lineage cells promotes tumor growth by inhibiting antigen presentation and phagocytotic functions of macrophages." (PMID 38424542, 2024). "CD244 was conducive to forming the immunosuppressive tumor microenvironment and the growth of HNSC in mice." (PMID 38633624, 2024). "Based on the datasets collected in the TCGA, GEO, and CPTAC databases, we systematically explored the CD244 gene expression, genetic alterations, promoter methylation, CD244-related prognosis and other molecular characterizations in 33 different tumor types." (PMID 38633624, 2024). "In an attempt to explore the biological function of CD244 among various tumor tissues, we collected CD244-binding proteins and CD244 co-expression genes to analyze functional enrichments and signaling pathways." (PMID 38633624, 2024). "To delineate the molecular pathways downstream of CD244 in monocyte-lineage cells, we analyzed the previously reported mouse syngeneic tumor single-cell RNA sequencing (scRNA-seq) dataset (GSE121861)." (PMID 38424542, 2024). "Flow cytometry and RNA sequencing data demonstrated a significant upregulation of CD244 expression in response to ER stress within the tumor mass." (PMID 38424542, 2024).